LINC01356 (long independently transcribed non-coding RNA 1356)
Synonyms: LIMp27
Gene: Long non-coding RNA gene on chromosome 1 (112,820,170 to 112,850,643, reverse strand). Ensembl gene ENSG00000215866.
Diseases named in the same sentence as LINC01356 in open-access papers:
LINC01356 is named in the same sentence as 6 diseases in open-access papers, as found by Europe PMC text mining. Sharing a sentence is not in itself a finding about the gene and the disease. The quoted sentences say what the papers report.
lung cancer (2 papers, 2022 to 2023). A malignant neoplasm involving the lung. "In addition, LINC01356 was higher in the plasma of lung cancer patients with brain metastasis, which means that LINC01356 could be a predictive factor of the likelihood of brain metastasis." (PMID 35574344, 2022).
cancer (2 papers, 2021 to 2023). A tumor composed of atypical neoplastic, often pleomorphic cells that invade other tissues. "Moreover, we found two key TFs (EPO, ARID3A), four key PRSGs (CACNA1E, LINC01356, CGA and SSX3) and five key hallmarks of cancer gene sets (DNA repair, myc targets, E2F targets, mTORC1 signaling and unfolded protein response) in the regulatory network." (PMID 33816287, 2021).
LINC01356 also shares sentences with these, for which no sentence is quoted: breast carcinoma (1 paper); colon adenocarcinoma (1); colon adenoma (1); tumor (1).